GNA13 (G protein subunit alpha 13)
Diseases named in the same sentence as GNA13 in open-access papers (continued):
Sharing a sentence is not in itself a finding about the gene and the disease.
tumor (continued). "miR-30b can inhibit the PI3K/AKT (phosphoinositide 3-kinase/protein kinase B) signaling pathway through the regulation of EGFR, AKT, Derlin-1, GNA13), SIX1, and other target genes, thus inhibiting the epithelial–mesenchymal transition process of tumor cells and promoting apoptosis." (PMID 40075907, 2025). "GNA13 is regarded as a tumor suppressor in DLBCL, and altered GNA13 signaling could enhance the proliferation and survival of B cells in the TME, leading to B cell–rich neighborhoods." (PMID 40772779, 2025). "Moreover, miR-30b can inhibit the PI3K/AKT signaling pathway through the regulation of EGFR, AKT, Derlin-1, GNA13, SIX1, and other target genes, thus inhibiting the EMT process of tumor cells and promoting apoptosis." (PMID 35291564, 2022). "Data shown here indeed support this notion that GNA13 can induce tumor-initiating phenotype independent of EMT induction." (PMID 29255247, 2018). "To validate these findings, we analyzed GNA13 protein expression by immunohistochemistry in 145 HNSCC tumor tissues, from patients that had no prior treatment." (PMID 29255247, 2018). "To determine whether GNA13 induces TIC-like phenotype in vivo, we injected 5 × 105, 5 × 104, and 5 × 103 NCC-HN26 cells stably expressing either the vector alone or GNA13 in NOD/SCID mice subcutaneously, and monitored tumor growth." (PMID 29255247, 2018). "Indeed, several of the identified genes in our study are reported to be involved in angiogenesis, tumor angiogenesis and arteriogenesis, i.e. IL-8, ET-1, CARP, HPTPη, ID1, MGSA, SMAD7, HO-1, RHOB, PTHLH, SERPINH1/HSP47, JAG1, GNA13 and TEAD4." (PMID 16594992, 2006). "Interestingly, converse depletion of CCL2 led to a decrease in tumor size and TAM recruitment only in the background of GNA13 loss, but not in GNA13 wild-type tumors, proposing pharmaceutical targeting of CCL2 in GNA13-mutant cancers as a possible therapeutic intervention to be further investigated." (PMID 35027544, 2022). "The three GNA13 palmitoylation mutants, on the contrary, did not inhibit proliferation of SU-DHL4-shGNA13UTR, further demonstrating that palmitoylation of GNA13 is required for its tumor suppressor function." (PMID 33423045, 2021).
cancer (23 papers, 2014 to 2024). A tumor composed of atypical neoplastic, often pleomorphic cells that invade other tissues. "While one previous study had demonstrated a correlation between low GNA13 levels and sensitivity to Gemcitabine, our data suggest a more fundamental cancer trait that underlies an almost universal resistance to cytotoxic treatment." (PMID 29255247, 2018). "These analyses showed that tumors with high GNA13 mRNA expression were associated with poor survival in the head and neck (p = 0.031) cancers." (PMID 29255247, 2018). "Guanine nucleotide binding protein (G protein), alpha 13 (GNA13) has been implicated as an oncogenic protein in several human cancers." (PMID 26735177, 2016). "Recently, overexpression of GNA13 has been observed in several human cancers and was associated with cancer development and progression." (PMID 26735177, 2016). "The detection of GNA13 expression status might be served as an integrated approach for identifying HCC patients at high risk of cancer progression." (PMID 27883022, 2016). "Previously, we also underlined that increased expression of GNA13 could accelerate the G1/S phase transition, thereby promoting cancer cell proliferation and tumorigenesis probably due to modulation of c-Myc and FOXO1 activity." (PMID 27883022, 2016). "Further, loss of miR-31 and gain of GNA13 may be viable biomarkers for assessment of breast and other cancers." (PMID 25889182, 2015). "By affecting the palmitoylation of GNA13, these cancer cells with a wild-type GNA13 protein became again sensitized to a BCL2 inhibitor, suggesting GNA13 palmitoylation as potential target for combinatory therapy with BCL2 inhibitors." (PMID 36226054, 2022). "Broadening the search to genes previously associated with other cancer types in Cancercensus, we identified three other genes overlapping with CpG sites identified as candidate CpGDMs (HMGA2, GNA13, and STK33)." (PMID 33145876, 2021). "Some proteins of the guanine nucleotide‐binding protein subunits GNAQ (Gqα), GNAS (Gs‐α), GNB1(Gβ1), and GNA13 (Gα) were overrepresented in the Circadian entrainment pathway as well as in cancer pathway." (PMID 31282103, 2019). "Most studies have focused on the role of GNA12 in cancer biology; however, few studies have reported the specific role of GNA13." (PMID 26735177, 2016). "Our data suggest that GNA13 overexpression in HCC cells led to cancer progression and tumorigenesis via other signalling pathways." (PMID 27883022, 2016). "Guanine nucleotide binding protein alpha 13 (GNA13) has been found to play critical roles in the development of several human cancers." (PMID 27883022, 2016). "Of note, there are more studies which focus on the role of GNA12 in cancer biology, while less was studied about the specific role of GNA13." (PMID 27883022, 2016). "Both GNA12 and GNA13 are known to be upregulated in aggressive cancer cells as well as advanced cancer tissues in several cancer types." (PMID 25889182, 2015). "Since most of the previous studies focused on GNA12, we have recently begun to assess the specific role(s) of GNA13 in cancer cell invasion, and the control of its expression in cancers." (PMID 25889182, 2015). "We will test the role of palmitoylation of GNA13 in other type of cancer in the future." (PMID 33423045, 2021). "Another hub gene, such as KITLG, PTGS2, SYK, FLT1 (VEGFR-1), GNA13, etc. could also regulate invasion and metastasis of cancer 42-48." (PMID 32194783, 2020). "IHC analysis in two large GC samples showed that expression levels of GNA13 appeared to increase with cancer progression: a significant increase in GNA13 expression was observed from normal gastric tissues to early stage GC samples, and from early stage to advanced stage GC samples." (PMID 26735177, 2016). "All these data implied that the role of GNA13 in human cancer is tissue-specific." (PMID 27883022, 2016). "In addition, we show that GNA13 induces TIC-like phenotype in HNSCC cancer cells." (PMID 29255247, 2018).
cancer (continued). "Furthermore, high levels of GNA13 were mainly found in the cytoplasm of carcinoma cells." (PMID 27883022, 2016). "Hence, identifying the specific mechanism(s) of GNA13 regulation in breast and other cancers could potentially lead to the development of miRNA-based therapeutic strategies for these cancers." (PMID 25889182, 2015). "In addition to the most-commonly altered COSMIC Tier 1 genes, there is a long tail of both cancer-associated and other mutated genes that may play a role in urothelial carcinogenesis and require further investigation; examples include BIRC6, the catalytic arg-200 of GNA13, and Q383H in AHR." (PMID 35655252, 2022). "Analysis of cancer genomics databases show that GNA13 (but interestingly not GNA12) is indeed a strong prognostic marker for poor survival and metastasis in a range of solid tumors: head and neck, ovarian, lung and gastric." (PMID 29255247, 2018). "In this study, we uncovered a crucial role of GNA13 in the acquisition of TIC-like phenotypes and therapeutic response in solid tumors, and found that GNA13 expression levels correlate with poor clinical outcomes in these cancers." (PMID 29255247, 2018). "For example, we found the SE hijacking event of a cancer-related gene, GNA13 in BT474, but NeoLoopFinder could not detect it." (PMID 39322849, 2024). "Additionally, analysis of expression profiles of the NCI-60 panel of cancer cell lines showed that GNA13 mRNA levels, but not GNA12, correlate significantly with the CSC/TIC marker ALDH1 (p = 0.037)." (PMID 29255247, 2018). "It is not clear whether GNA13 also regulates the expression of BCL2 in tumors other than GCB-DLBCL and whether the therapeutic scenario for targeting palmitoylation of GNA13 in combination with the BCL2 inhibitor holds in other types of cancer." (PMID 33423045, 2021).
infection (3 papers, 2011 to 2023). The state of being infected such as from the introduction of a foreign agent such as serum, vaccine, antigenic substance or organism. "We found that genes of the Calcium signaling pathway were all significantly downregulated at 24 and 48 h post-infection, such as GNA13, ARGHGEF12, ROHA, ROCK1, and MYL12A." (PMID 37211158, 2023). "The topological plots showed that GNA13 and ARHGEF12 were significantly downregulated at 48 h post-infection, and these genes inhibit the Calcium signaling pathway by regulating ROCK1 and MYL12A." (PMID 37211158, 2023). "The real-time RT-PCR also revealed that the changes on gene expression of IL-10, GNA13 and TLR3 are not significantly changed at these early time points even at 100 MOI infection." (PMID 22028943, 2011).
GNA13 also shares sentences with these, for which no sentence is quoted: follicular lymphoma (4 papers); bladder cancer (2); Alzheimer disease (1); cervical carcinoma (1); COVID-19 (1); cytomegalovirus infection (1); dilated cardiomyopathy (1); glioblastoma (1); head and neck cancer (1); human immunodeficiency virus 1 (1); Hyperglycemia (1); Insulin resistance (1); liver cancer (1); metastatic melanoma (1); Neurological Disorder (1); Osteopenia (1); prostate adenocarcinoma (1); sarcopenia (1); skin melanoma (1); small cell lung carcinoma (1); squamous cell carcinoma (1); testicular cancer (1); virus infections (1).